FOXA1 (forkhead box A1)
Diseases named in the same sentence as FOXA1 in open-access papers (continued):
Sharing a sentence is not in itself a finding about the gene and the disease.
prostate carcinoma (continued). "As a transcription factor, FOXA1 can bind to androgen receptor (AR) and is highly expressed at the early stage of prostate cancer." (PMID 35968505, 2022). "Altogether, this strongly suggests that FOXA1’s pioneering activity contributes to prostate cancer tumorigenesis by influencing the AR cistrome." (PMID 36212399, 2022). "In summary, our results indicate that ivermectin suppressed the AR and E2F signaling pathways and DNA damage repair capacity by targeting FOXA1 and Ku70/Ku80 to inhibit cell proliferation and promote cell apoptosis in prostate cancer." (PMID 36050295, 2022). "Evaluation of 20 androgen target genes in primary prostate cancer indicates that various patterns exist, depending on the presence of the ETS fusion or mutations in SPOP or FOXA1." (PMID 35682963, 2022). "This, in combination with the finding that FOXA1 is a key transcription factor in mCRPC models that rely on the AR signaling axis, posits FOXA1 as a crucial contributor to AR-dependent prostate cancer progression." (PMID 36212399, 2022). "FOXA1 can also regulate the transcription and translation of AR genes and increases androgen synthesis, which results in the promotion of prostate cancer cell metastasis." (PMID 35968505, 2022). "Our study identifies the SWI/SNF complex as a transcriptional dependency in AR/FOXA1-driven prostate cancer." (PMID 34937944, 2022). "Androgen receptor (AR)+ forkhead box A1 (FOXA1)+ prostate cancer cells are exquisitely sensitive to dual SMARCA2 and SMARCA4 degradation relative to normal and other cancer cell lines." (PMID 34937944, 2022). "We and others have demonstrated that transcription regulators, such as FOXA1, promote prostate cancer progression and resistance to ART and ADT." (PMID 35550030, 2022). "For example, in in vitro models of prostate cancer, the BET inhibitor JQ1 interacts with FOXA1 and prevents it from repressing genes implicated in epithelial-to-mesenchymal transition, resulting in invasive phenotypes." (PMID 36212399, 2022). "This is analogous to the prior observation that FOXA1 binds to the androgen receptor enhancer and regulates its expression in prostate cancer cells." (PMID 35703180, 2022). "FOXA1 helps to shape AR signaling through direct interactions with the AR and drives the growth and survival of normal prostate and prostate cancer cells." (PMID 35627227, 2022). "The expressions of AR, MYC and FOXA1 genes themselves are frequently amplified in advanced prostate cancer by copy amplification and/or enhancer duplication." (PMID 34937944, 2022). "Altogether, our study revealed an intricate crosstalk between the AR, MYC, FOXA1 and RNA Pol II resulting in a corrupted AR transcriptional program and promoting prostate cancer initiation and progression to the mCRPC stage." (PMID 35562350, 2022). "In many cases, such as for AR, MYC, and FOXA1, these hotspots overlap with active chromatin marks and likely represent distal regulatory regions for neighboring prostate cancer genes, as shown by our analyses overlapping SVs with ChIP-Seq on mCRPC specimens." (PMID 35943799, 2022). "De novo motif and binding analysis for the regulation of transcription (BART) analyses of AU-15330-compacted sites identified DNA-binding elements for major oncogenic transcription factors in prostate cancer, including AR, FOXA1, HOXB13 and ERG." (PMID 34937944, 2022).
prostate carcinoma (continued). "It is well established that cancer-cell proliferation is impaired upon FOXA1 depletion since ER and AR transcription is FOXA1-dependent both in breast and prostate cancer cells." (PMID 36230619, 2022). "Studies using a variety of prostate cancer cell lines later demonstrated that FOXA1 overexpression or knock-down reprograms the AR cistrome." (PMID 36212399, 2022). "For example, it has recently been shown that androgen receptor (AR) and forkhead box A1 (FOXA1) expressing prostate cancer cells are sensitive to simultaneous degradation of BAF complex subunits SMARCA2, SMARCA4 and PBRM131." (PMID 36216795, 2022). "Loss of the NKX3-1 homeobox gene is a frequent and early event in prostate cancer etiology while the TMPRSS2-ERG gene fusion and FOXA1 mutations both identify major molecular subtypes of the disease." (PMID 35562350, 2022). "Foxa1 establishes competence in the foregut endoderm and plays roles in mammary and prostate cancer." (PMID 34387762, 2022). "Inflammatory response genes have been found to be upregulated in the tumors of prostate cancer patients with low FOXA1 expression." (PMID 35892678, 2022). "The pioneering factor FOXA1 modulates chromatin accessibility, directly interact with AR and shapes its signalling driving prostate cancer tumor growth." (PMID 36251389, 2022). "Altogether, owing to its role in pioneering, or unpacking the chromatin, for the AR, FOXA1 poses as a key prostate cancer-specific regulator of disease progression and therapeutic response." (PMID 36212399, 2022). "identify the pioneer transcription factor FOXA1 as a master regulator of alternative splicing in prostate cancer." (PMID 36170835, 2022). "FOXA1 is a critical dependency in prostate cancer cell line models, including those that transdifferentiate into AR-agnostic, neuroendocrine-like features." (PMID 35550030, 2022). "Given the established role of FOXA1 in regulating AR activity in prostate cancer, much interest has been focused on the interplay between FOXA1 mutations and the AR cistrome." (PMID 36212399, 2022). "FOXA1 is reported to be an oncogene in a variety of cancers, including thyroid cancer, lung cancer, oesophageal cancer, and prostate cancer." (PMID 35479097, 2022). "FOXA1 is a driver for prostate cancer and breast cancer, whereas plays a tumor suppressive role in nasopharyngeal carcinoma." (PMID 35974000, 2022). "Overall, we report a role for FOXA1 in rewiring the alternative splicing landscape in prostate cancer through a cascade of events from chromatin access, to splicing factor regulation, and, finally, to alternative splicing of exons influencing patient survival." (PMID 36170835, 2022). "While the impacts of these pharmacological inhibitors on FOXA1 activity and prostate cancer growth are still limited to the preclinical stage, there are opportunities to test these findings clinically." (PMID 36212399, 2022). "Several pioneer transcription factors are recognized as drivers of prostate cancer initiation and progression, including the forkhead box A1 (FOXA1) transcription factor, the homeobox protein HOXB13, and the GATA binding protein 2 (GATA2)." (PMID 36212399, 2022). "We find that BRG1 promotes gene expression in prostate cancer models with varying degrees of dependence on AR and FOXA1." (PMID 33596994, 2021). "In the genomic locus of HOXA11-AS, we found androgen receptor (AR)- and forkhead box A1 (FOXA1)-binding sites, which are key components in prostate cancer development and progression." (PMID 33514011, 2021). "Overlaying the prostate cancer epigenome reveals a catalog of CREs critical for FOXA1 mRNA expression that are extensively perturbed through various modes of somatic mutations." (PMID 32946061, 2021). "Recent studies looking at the implications of FOXA1 across different stages of prostate cancer revealed new functional roles relevant for prognosis, therapeutic response and targeted therapy." (PMID 32946061, 2021).
prostate carcinoma (continued). "FOXA1 is accessible across most prostate cancer cells and CDX2 shows higher accessibility, specifically in one of the Gleason pattern 4 tumours." (PMID 34911933, 2021). "Despite these previous findings, our understanding of the mechanisms and the extent of FOXA1 involvement in prostate cancer remains incomplete." (PMID 32946061, 2021). "AR is a well-established oncogenic driver and therapeutic target in prostate cancer, and the requirement of FOXA1′s pioneering function for AR activation and disease progression is well established." (PMID 34680352, 2021). "In this review, we summarize the recent research on FOXA1 in prostate cancer and offer a perspective on the clinical value of FOXA1 given these findings." (PMID 32946061, 2021). "So, in the future, more depth researches on transcription factor FOXA1 in prostate cancer are needed." (PMID 34445492, 2021). "Our epigenomic analyses focused on androgen receptor (AR), which is a key oncogenic driver in prostate cancer, the AR pioneer factor FOXA1, chromatin insulator CCCTC‐Binding Factor, as well as for modified histones H3K27ac and H3K27me3." (PMID 33576154, 2021). "For example, a higher frequency of mutations in FOXA1, the gene encoding a pioneer factor that facilitates AR chromatin binding and transcriptional activation, was found in CRPC (12%) than in primary prostate cancer (4%)." (PMID 34630112, 2021). "Through direct interactions with the Androgen Receptor (AR), FOXA1 helps to shape AR signaling that drives the growth and survival of normal prostate and prostate cancer cells." (PMID 32946061, 2021). "BRG1 is required to drive the expression of numerous prostate cancer specific genes in an AR/FOXA1 dependant manner, but also works independently to drive the expression of pro-proliferative and DNA replication genes." (PMID 33596994, 2021). "These SNVs and SNPs add another layer of complexity whereby FOXA1 confers prostate cancer complexity to the regulation of FOXA1 cistrome." (PMID 32946061, 2021). "These mutations also enhance FOXA1 association with DNA but reduce its interaction with TLE3, a transcriptional corepressor of Wnt signaling in prostate cancer cells." (PMID 34680352, 2021). "Along with altered ability to induce chromatin accessibility, FOXA1 mutants can induce an unique epigenetic landscape that is distinct from wild-type FOXA1 in prostate cancer." (PMID 32946061, 2021). "Many studies have shown that FOXA1 participates in the development of lung cancer, prostate cancer, and several other types of cancers." (PMID 33686019, 2021). "This is consistent with the well-established role of FOXA1 as a major AR co-regulator and pioneer factor in prostate cancer cells, and the emerging role of FOXM1 in this capacity as well." (PMID 33513133, 2021). "22RV1 prostate cancer cells expressing FOXA1 C-terminal truncation mutants showed an accumulation of transcriptionally active β-catenin, indicative of WNT pathway activation." (PMID 32946061, 2021). "The analysis into the Chinese Prostate Cancer Genome and Epigenome Atlas (CPGEA) cohort revealed FOXA1 mutation in 41% of localized prostate tumours, a rate significantly higher than Western cohorts." (PMID 32946061, 2021). "In this review, we describe the latest discoveries related to the function and regulation of FOXA1 in prostate cancer, pointing to their relevance to guide future clinical interventions." (PMID 32946061, 2021). "Among recurrent mutations specific to 2-kupl, we note the one found at chr14:37592023 within an exon of FOXA1, a putative prostate cancer driver, in three TCGA-PRAD patients." (PMID 34090332, 2021). "We discovered that the most significantly enriched datasets were for the AR and FOXA1, both of which are important for prostate cancer growth." (PMID 33596994, 2021). "Following up on FOXA1 mRNA expression levels, we interrogated the essentiality of FOXA1 for prostate cancer cell growth." (PMID 31974375, 2020).
prostate carcinoma (continued). "Our studies demonstrate that HOXC4 and HOXC6 co-localize with HOXB13, FOXA1 and AR, three transcription factors previously shown to contribute to the development of prostate cancer." (PMID 32012197, 2020). "By leveraging these technologies, we can begin to understand the three-dimensional organization of the prostate cancer genome and delineate the FOXA1 regulatory plexus." (PMID 31974375, 2020). "The Hi-C data from the LNCaP prostate cancer cells corroborates the C3D predictions as demonstrated by the elevated contact frequency between the region harboring the FOXA1 promoter and where the six CREs are located, compared with other loci in the same TAD." (PMID 31974375, 2020). "RNAi-mediated essentiality screens compiled in DEPMAP show that FOXA1 lies in the 94th percentile across six of the eight available prostate cancer cell lines: 22Rv1, LNCaP, MDA PCa 2B, NCI-H660, PC3, and VCaP cells." (PMID 31974375, 2020). "According to chromatin contact frequency maps generated from Hi-C assays performed in LNCaP prostate cancer cells, FOXA1 lies in a 440 kbp TAD (chr14: 37720002–38160000 ± 40 kbp adjusting for resolution)." (PMID 31974375, 2020). "The FOXA1 protein is required for epithelial cell differentiation in the mouse prostate and promotes cell cycle progression in castration-resistant prostate cancer." (PMID 32235312, 2020). "Increasing researches have indicated that FOXA1 expresses at high levels in many cancers, such as lung cancer, glioma and prostate cancer." (PMID 32831649, 2020). "Taken together, we identified FOXA1 CREs targeted by SNVs that are capable of altering transactivation potential through the modulation of key prostate cancer TFs." (PMID 31974375, 2020). "More recently, three distinct classes of alterations in FOXA1 have been described in prostate cancer, each with unique structural and phenotypic consequences." (PMID 33062889, 2020). "As FOXA1 is essential for prostate cancer growth, we next sought to assess the importance of the six FOXA1 plexus CREs towards prostate cancer cell growth." (PMID 31974375, 2020). "We next analyzed expression data from DEPMAP and observed FOXA1 to be most highly expressed in prostate cancer cell lines compared with cell lines of other cancer types." (PMID 31974375, 2020). "FOXA1 was found to be predominantly confined to the nucleus of epithelial prostate cancer cells as well as in adjacent benign tissue." (PMID 32655839, 2020). "Here, authors identify a set of six cis-regulatory elements in the FOXA1 regulatory plexus harboring somatic SNVs in primary prostate tumors and characterize their role in regulating FOXA1 expression and prostate cancer cell growth." (PMID 31974375, 2020). "Understanding how FOXA1 is expressed can provide a complementary strategy to antagonize FOXA1 in prostate cancer." (PMID 31974375, 2020). "HOXB13 acts as a transcription factor and, together with the androgen receptor (AR) and FOXA1, regulates expression of the RFX6 gene which encodes a driver of prostate cancer progression." (PMID 32546843, 2020). "We find that deletion and repression of these cis-regulatory elements significantly decreases FOXA1 expression and prostate cancer cell growth." (PMID 31974375, 2020). "Collectively, these studies combined with our discoveries reveal the fundamental contribution of the FOXA1 plexus in prostate cancer etiology." (PMID 31974375, 2020). "Aligning with recent reports, our findings support the oncogenic nature of FOXA1 in prostate cancer." (PMID 31974375, 2020). "In prostate cancer, FOXA1 also influences the ability of AR to bind DNA and control cell cycle progression." (PMID 33062889, 2020). "Levels of FOXA1 are also elevated in prostate tumors and metastases, and overexpression of FOXA1 in prostate cancer cell lines results in increased AR binding at novel sites that have high chromatin accessibility." (PMID 33062889, 2020).
prostate carcinoma (continued). "In summary, IGF-I and hyperglycaemia-induced FOXA1/IGFBP-2 play important roles in promoting prostate cancer cell progression." (PMID 32655839, 2020). "The median RNAi-mediated essentiality score for all prostate cell lines is significantly lower than all other cell lines, suggesting that FOXA1 is especially essential for prostate cancer cell proliferation (permutation test, p = 1 × 10−6)." (PMID 31974375, 2020). "The SE-associated lineage-specific machinery of ERG is linked with the TFs like FOXA1 and HOXB13, which play important roles in prostate-cancer-specific gene expression." (PMID 33299103, 2020). "We observe that these six CREs can be bound by multiple TFs in prostate cancer cells, including FOXA1, AR, and HOXB13." (PMID 31974375, 2020). "Role of FOXA1 has been elaborated in many cancers, prostate cancer cell proliferation and cancer progression was mediated through FOXA1 by targeting the tumor suppressor gene IGFBP-3." (PMID 33344262, 2020). "Rationale: The forkhead box A1 (FOXA1) is a crucial transcription factor in initiation and development of breast, lung and prostate cancer." (PMID 32929382, 2020). "We used the DHS profiled in prostate cancer cells to identify putative FOXA1 CREs by annotating these regions with five different histone modifications, TF-binding sites and noncoding SNVs profiled in prostate cancer cells and primary prostate tumors." (PMID 31974375, 2020). "In prostate cancer, FOXA1 is known to pioneer and reprogram the binding of the androgen receptor (AR) alongside HOXB1318." (PMID 31974375, 2020). "In accordance with previous reports, our results using essentiality datasets followed by knockdown validation reveals that FOXA1 is oncogenic and essential for prostate cancer cell proliferation." (PMID 31974375, 2020). "Motivated by the oncogenic role of FOXA1 in prostate cancer, we investigated its regulatory plexus controlling its expression." (PMID 31974375, 2020). "Anchoring our analysis to the FOXA1 promoter and using accessible chromatin regions defined in LNCaP prostate cancer cells identified 55 putative CREs to the FOXA1 regulatory plexus (r > 0.7)." (PMID 31974375, 2020). "In prostate cancer, FOXA1 is indispensable in androgen receptor (AR)-mediated gene regulation by interacting directly with AR and co-occupying chromatin." (PMID 32929382, 2020). "On the contrary, NDRs in prostate cancer-specific enhancers involved in enhancer–promoter loops are enriched for motifs for TFs such as FOXA1, GRHL2, ETS, and AR." (PMID 31515496, 2019). "To gain insights into essential binding sites in a different cell lineage, we performed the same screening experiment in the LNCaP prostate cancer cell line, where FOXA1 is also known to be essential." (PMID 31727847, 2019). "Using ChIP-seq data for the most enriched TF FOXA1, we also revealed target genes of prostate-cancer-specific enhancers." (PMID 31515496, 2019). "Studies in prostate cancer specimens confirmed reduced FOXA1 levels and increased TGFβ signaling in CRPC specimens compared to primary tumors." (PMID 31366128, 2019). "Selective targeting of PARP-2 by genetic or pharmacological approaches blocks the interaction between PARP-2 and FOXA1, attenuating AR-mediated gene expression and inhibiting AR-positive prostate cancer growth." (PMID 31366128, 2019). "RNA-seq analysis indicates that FOXA1 is upregulated in prostate cancer cells (fold change > 498.3, adj." (PMID 31515496, 2019). "To illustrate the sensitivity of the optimized protocol, we provide high-quality ChIP-seq data for three independent factors (AR, FOXA1, and H3K27ac) from a single core needle prostate cancer biopsy specimen." (PMID 30620009, 2019). "AR showed a broad spectrum of activity between genomic subtypes: ETS fusion-positive prostate cancers display a variable AR transcriptional activity; tumors with SPOP or FOXA1 mutations had the highest AR transcriptional activity." (PMID 31366128, 2019).